IL1B (interleukin 1 beta)
Diseases named in the same sentence as IL1B in open-access papers (continued):
Sharing a sentence is not in itself a finding about the gene and the disease.
infection (continued). "Likewise, brain tissues of animals with S. epidermidis-infected catheters had higher levels of IL-10 (P < 0.001), IL-1β (P < 0.001), CCL2 (P < 0.001), and CCL3 (P < 0.001) at day 1 postinfection, demonstrating that the CSF inflammatory milieu mirrors that of the brain tissue during early infection." (PMID 31262978, 2019). "However, in the presence of LL-37, a 3 hour infection with PAO1 led to an increase in caspase-1 activated NHBE cells (to ~16%) and 16HBE14o- cells, significantly greater than to LL-37 or PAO1 alone, with the same synergistic pattern observed as for IL-1β release." (PMID 30978238, 2019). "We found increased levels of IL-1β, CCL2, and CCL3 concomitant with elevated neutrophil infiltrates in the CSF of animals with S. epidermidis-infected catheters, which may serve as potential markers for distinguishing infection from sterile postoperative inflammation in humans." (PMID 31262978, 2019). "The action of IL10 appears to be solely responsible for the suppression of IL1B and IL6 production during G18 infection, thus supporting our hypothesis that IL10 induced during G18 infection is dampening down some of the transcriptional response of bMDM to infection." (PMID 31527895, 2019). "IL-1β that was found upregulated in lymphocytes and not differentially expressed in monocytes, is a potent inflammatory cytokine involved in the recruitment of immune and inflammatory cells into the site of infection and influences the development of adaptive immune responses." (PMID 31333643, 2019). "Indeed, while IL-1β secretion is equally affected regardless of whether PEGs are present during or after the infection, cell death is only inhibited when PEGs are present during the post-infection phase." (PMID 31275321, 2019). "Given that several such cytokines, such as TNF, IL‐1β, and IL‐6, are potent, nonredundant mediators of anti‐TB immunity, it is perhaps not surprising that their regulatory pathways represent attractive targets for dampening the host immune response to infection." (PMID 29345343, 2018). "However, CASP1 activation during G18 infection was not statistically significantly higher than that observed in uninfected bMDM due to the level of variation in the biological replicates, as with the IL-1β ELISA results." (PMID 29263113, 2018). "Furthermore, most of the pro-inflammatory genes found on this array, which we have previously identified to be increased with 22L infection (such as Cxcl10, Ccl8, Tnf, IL1a, and IL1b), were similarly increased in the absence of TLR2 or C5aR1 signaling during scrapie infection." (PMID 30596651, 2018). "However, in vitro infection or treatment of intestinal epithelial cells by T. gondii or LPS did not trigger an IL-1β or IL-18 response regardless of whether the P2X7R was present, suggesting that in epithelial cells P2X7R may have an alternative role." (PMID 27559003, 2017). "Tnf and Il1b, which were found to be up-regulated in this study, could promote the transcription and expression of Ptx3, a humoral pattern recognition receptor and nonredundant component of humoral innate immunity for anti-infection." (PMID 28899359, 2017). "Interestingly, WT infection does not induce production of the canonical chemokines IL-1β and IL-8 at this time during the infection; MIP-1α or other signals outside of our screening assay may be responsible for the PMN recruitment to the site of infection." (PMID 29176665, 2017). "Interestingly, despite the differences found in IL-1β mRNA expression levels 12 and 16 weeks post-infection in WT infected footpads, we could not observe augmented levels of this cytokine in dLNs of WT in all periods measured when compared to gp91phox−/− dLNs." (PMID 27056545, 2016).
infection (continued). "Additionally, in vitro, endocytosis of HCV and HIV virions by blood monocytes or plasmacytoid dendritic cells can induce production of interferon or IL-8 as well as activation of the NLRP3 inflammasome to produce and release IL1-β without requiring a productive infection of the cell itself." (PMID 27649908, 2016). "In contrast, IOE infection that fails to induce memory-like NK cells or provide a protective recall response to Ehrlichia promoted the production of inflammasome-dependent, pro-inflammatory cytokines, including IL-1α, IL-1β, and IL-18 (data not shown), and the immunosuppressive IL-10." (PMID 27092553, 2016). "This discrepancy may be due to the fact that KSHV may be undergoing abortive infection in the PMA stimulated cells as has been shown for HSV-1 in these cells and DNA released from the lysosomes is probably recognized by AIM2, c-GAS, and others to stimulate the IL-1β and interferon responses." (PMID 26134128, 2015). "Interestingly, IL-20 has been previously shown to play a rather negative role in host defense; infection with Staphylococcus aureus led to the early up regulation of IL-20 family members (IL-19, IL-20 and IL-24), inhibiting the local generation of IL-1β and IL-17A." (PMID 26023727, 2015). "The same group showed that mice deficient in both IL-1β /IL-18 are more susceptible than C57BL/6J mice, yet not as much as mice deficient in ASC or caspase-1, suggesting that other caspase-1-dependent pathways, most likely pyroptosis, significantly contributed to protection from infection." (PMID 25768794, 2015). "However, although ASC is necessary for robust secretion of IL-1β in response to L. pneumophila as well as a number of pathogens, such as Salmonella or Yersinia species which employ T3SSs, ASC is dispensable for induction of pyroptosis that is rapidly triggered in response to these infections." (PMID 23762026, 2013). "Our data reveal that 1,25D is acting primarily at the level of IL1B gene transcription without affecting the levels of inflammasome, as substantial levels of pro-IL-1β were seen in uninfected macrophages after 1,25D treatment, whereas secretion required infection." (PMID 23762029, 2013). "We thus propose that the presence of IL-1α or IL-1β is sufficient to trigger IL-1R pathway, an essential component in the development of innate response to acute M. tuberculosis infection, but may not be sufficient for full control of the infection." (PMID 25400917, 2013). "However, when macrophages were isolated from mice immunized with MVAwt or MVA derivatives six days before, in vitro infection of these cells with MVAΔIL-1βR again resulted in IL-1β production, regardless of the immunizing virus used (immunization: MVA variants)." (PMID 23356675, 2013). "Because NLRP3 activation leads to caspase-1 activation and consequent IL-1β secretion, we next asked whether caspase-1 and IL-1β are required for NLRP3-dependent NO production in response to T. cruzi infection, and what role these molecules play in the control of infection by macrophages." (PMID 24098823, 2013). "The deficiency in mature IL-1β release in these cells was not due to reduced or missing adenovirus infectivity, since similar fluorescence levels of GFP could be detected in all cell lines 24 h post infection." (PMID 23935506, 2013). "However, whether M. kansasii, a slowly growing NTM, infection could induce caspase-1 activation and IL-1β secretion via the inflammasome activation has not been reported yet." (PMID 22558425, 2012). "However, the difference in kinetics of DsRed fluorescence signals were less than 24 hrs and thus would be unlikely to impact the approximation of IL-1β production in vivo, since we began our measurements 1 day after infection and the infection takes over 14 days to resolve." (PMID 23209417, 2012).
infection (continued). "Specifically, IL-1β and TNF-α signalling are negatively regulated by IL-6 and may compensate for the loss of IL-6, which could explain why IL-6−/− mice were not protected during H1N1pdm infection." (PMID 22679491, 2012). "For the cytokines Rantes, GM-CSF, Eotaxin, IL-13, IL-9, IL-6 and IL-1b there was no significant mean difference in concentration among the first three time-points (15 min, 30 min and 60 min) and the last two time-points (4 hrs and 10 hrs) for both the H37Rv and Δ-mce1 H37Rv-infections." (PMID 22039457, 2011). "In addition to the evidence that peripherally immune-derived cytokines can trigger neuro-endocrine responses during infection and inflammation, several non-immune functions of cytokines such as TNFα, IL-1β and IL-6 synthesised within the CNS in the absence of disease have been described." (PMID 19254758, 2009). "gonorrhoeae strain MS11mkC, we did not see similar increases in urine IL-6, TNF-α, or IL-1β, although differences in IL-6, TNF-α were observed in participants with later development of infection." (PMID 41810365, 2026). "To further examine the kinetics of NLRP11-dependent activation of the non-canonical inflammasome, we assayed IL-1β release in M. kansasii-infected WT and NLRP11∆N_LRR (Cas9) macrophages at 1, 2, 4, and 6 h of infection." (PMID 40272180, 2025). "Key findings revealed a surge in IL-1β expression in the kidney and SAA expression in the spleen at 5 days post-infection (dpi), coinciding with no visible symptoms." (PMID 40509043, 2025). "We measured Type 1 (IFN-γ, TNF-α, IL-2), Type 17 (IL-17, IL-22), and proinflammatory cytokines (IL-1α, IL-1β) in QuantiFERON (QFT) supernatants from TBI individuals with (TBI+Hel+) and without (TBI+Hel−) infection." (PMID 41583474, 2025). "A modest but significant reduction in IL-1β levels in the BAL was observed in Gsdme−/− mice at day 3, but not day 5 post-infection." (PMID 40481027, 2025). "In correlation to cytoplasmic viral icRNA expression, infection of iMGs with either WT or ΔGag-Pol/HIV-1, but not M10, resulted in IL-1β secretion." (PMID 40920844, 2025). "The AG234 infection primarily activated the immune response at 48 hpi, characterised by a significant mRNA up-regulation of TLR3, TLR21, IL-1β and INF-γ compared to the negative control." (PMID 40426284, 2025). "However, the absence of IL-1β significantly impacted immune defense and led to elevated fungal growth in both the kidney and brain, which is consistent with a 107-fold higher induction of Il1b transcripts compared to Il1a transcripts during the first two days post-infection." (PMID 40097388, 2025). "Prior to infection, animals that had been stimulated with live dpB (group 3) had higher IFN-γ, IL1-β TNF-α and IL-6 values than the group of inactivated dpB stimulated animals (group 1) or the infection controls (that had not been stimulated) (group 5)." (PMID 40969767, 2025). "The increase in IFNB and IL1B mRNA levels in PAMs and IFN-α protein in BAL MNPs upon infection, without significant differences between the NC strains, further confirms their similar pathogenetic mechanism." (PMID 41169353, 2025). "Akin to treatment with anti-IL-1β, anakinra did not improve survival after SARS-CoV-2 P21 infection in our model." (PMID 40016339, 2025). "Infection with two other IAV strains yielded similar results, indicating that the impact of NINJ1 on IL-1β release is not strain specific but rather a universal phenomenon." (PMID 40983621, 2025). "LAP inhibition did not affect proinflammatory cytokine secretion as the levels of IL-1β, TNF and IL-6 were not affected 24 hours post-infection of macrophages pretreated with SAR405 and GSK2795039, respectively." (PMID 40395986, 2025). "At MOI 30, Ad5-IκBαΔN and Ad5-GFP infection produced IκBαΔN or GFP protein, respectively, and, whereas Ad5-IκBαΔN inhibited NF-κB reporter activity induced by IL-1β, Ad5-GFP was without effect." (PMID 40972476, 2025).
infection (continued). "(A) Representative confocal images of GFP-AHPH localization with or without 1 ng/mL interleukin-1β (IL-1β) treatment in 0.5 multiplicity of infection (MOI) wild-type (WT) authentic SARS-CoV-2-infected HEK293T-ACE2 cells at 6 and 24 hr post-infection (hpi)." (PMID 39937682, 2025). "Now we found here that RVFV infection THP-1PMA, without the need of LPS priming, can trigger NLRP3 inflammasome and robust IL-1β release." (PMID 39213434, 2024). "A slight increase in IL-1β was observed only with M. bovis SB1564 at one week post-infection, however gene expression was evident also in non-infected samples and other infections." (PMID 38399810, 2024). "Regarding pituitary il1β, while no significant changes were observed in CTRL-fed fish, it significantly peaked in the TRP-fed group at 4 h post-infection." (PMID 38548769, 2024). "Compared to susceptible mice, CD-1 mice exhibited less fungal burden over 6 days of the infection, but similar neutrophil recruitment, IL-1β and alarmin S100A8 levels, with a declining but not significant trend over the infection." (PMID 39234208, 2024). "We observed that M. pneumoniae infection in vitro induced comparable mRNA expression of Il-1β, Il-6, and Tnf-α in WT neutrophils and Irg1 KO neutrophils compared to controls after 12h, suggesting that itaconate may not impact neutrophils expressing these cytokines during infection." (PMID 39499730, 2024). "A prior study reported the upregulation of IL-1β, IL-8, TNF-α, and IFN-γ in the kidneys of rainbow trout fed TC at the dose of 250 mg/kg for 60 days in the absence of infection." (PMID 38668265, 2024). "CCL-2 exhibited heightened levels on day 1 post-infection, while IL-1β, IL-13 and CCL11 showed increased levels on both day 1 and 4 post-infection, as compared to the non-infected group." (PMID 39038037, 2024). "None of the cytokines tested, except IL‐1β, at both RNA and protein levels, demonstrated a strong correlation with the LPA under infection conditions." (PMID 38976572, 2024). "Taken together, these findings demonstrate that the co-culture of P. gingivalis and F. nucleatum, rather than the monocultures or the separate infections with the bacteria, increases the expressions of TNF-α, IL-1β, IL-6, and IL-8 in OKs." (PMID 38612423, 2024). "IL-1β was abundantly released in the medium of N2aC24L1-3 cells, but not in N2aC24 cells, after IAV/WSN infection." (PMID 39194237, 2024). "Regardless of the infection stage in H1N1 and H3N2 infected mice, anti-IL-1β therapy reduced cellular infiltration and lung inflammation in the bronchoalveolar lavage fluid (BALF) and improved survival." (PMID 39459869, 2024). "We also tested TNF, IL-1β and IL-6 in BALF under homeostasis and observed no significant changes, though they began to trend higher on day 10 post-infection in ECSparcl1-OE mice." (PMID 38762489, 2024). "However, the addition of IL-1β, and/or IL-18 to macrophages at the time of infection did not suppress Legionella replication in Ipaf knockout macrophages, indicating that caspase-1 activation is critical for the clearance of the bacterium independently of the activity of IL-1β and IL-18." (PMID 39625520, 2024). "Compared to S. epidermidis 1457, hMDM infection with biofilm-negative mutant 1457-M10 as well as biofilm-positive, eDNA-negative 1457ΔatlE induced a significantly stronger expression of TNFA- and IL1B-response." (PMID 39567551, 2024). "Next, IL-1β and IL-18 released in the supernatant of untreated or HSV-1-infected cells expressing, or not, the ICP27 gene were quantified at 10 h post-infection by performing an ELISA assay." (PMID 38731826, 2024). "Following infection with intracellular pathogens, the lungs of B6.Sst1S congenic mice lacking SP110 exhibited a significant increase in IL-1β levels." (PMID 38891697, 2024). "For this work, we wanted to know if infection with cytopathic NADL and non-cytopathic NY-1 strains of BVDV would promote expression of IL-1β." (PMID 37515181, 2023).
infection (continued). "Infection with the total T3SS mutant 65ST, which does not induce any of the T3SS effectors, allowed maturation of pro-IL-1β into Il-1β, indicating that E. ictaluri T3SS effectors other than EseN are involved in the suppression of this response." (PMID 37796003, 2023). "Infection of PMA-matured THP-1 cells by both vaccine and WT MeV was sufficient to trigger inflammasome activation for production of IL-1β and IL-18 independent of extracellular virus production." (PMID 36851476, 2023). "After infection with SARS-CoV-2, cells from patients with AUD had a robust inflammatory response, including higher levels of TNFα, IL-1β, and IFNγ secreted than infected non-AUD cells." (PMID 37786945, 2023). "Using their protocol (3 h infection, no LPS priming), we also found that IL-1β secretion by PAO1 is NLRC4-dependent whereas our protocol (3 h priming, 1 h infection) is NLRC4 independent." (PMID 37730693, 2023). "Infection with a virulent BoHV-1 isolate (Iowa strain) elicited increased levels of pro-inflammatory TNF, but not IL-1β." (PMID 37112697, 2023). "The administration of MSCs to our model of established infection did not reduce the inflammatory cytokines TNF-α, IL-1β, or IFN-γ." (PMID 37175761, 2023). "Compared to infection without rAb-ADA, the co-administration of DENV-2 and rAb-ADA resulted in a substantial increase of inflammatory mediator genes IL-1β, IL-6, TNF-α, and CCL2 in Raw264.7 and THP-1 cells." (PMID 37794048, 2023). "Because MSCl cells did not produce pro-inflammatory TNFα and IL-1β upon L. casei CFS treatment in our experimental system, we decided to use the MSC cell line in our further viral-infection-mimicking experiments." (PMID 37371616, 2023). "In our case, skin despite showing the second highest viral loads of CEV, did not induce strong innate immune response, except IL-1β, the only gene that was up-regulated in koi carp during post-CEV infection." (PMID 37465154, 2023). "As in other myeloid cell types, LPS transfection or infection with the Gram-negative bacterial pathogen Citrobacter rodentium induces caspase-11 activation, GSDMD cleavage and IL-1β secretion in human and murine neutrophils." (PMID 37939552, 2023). "We showed that in response to B. pertussis, higher transcript levels of TNF, IL-1β, IL-6 and MIP-2α were detected 6 hours after infection when MPI were cultured without GM-CSF and therefore when STAT5 is inactivated." (PMID 37841236, 2023). "We found that SubAB reduced activation of the STEC O113:H21 infection-induced non-canonical NLRP3 inflammasome and interleukin (IL)-1β and IL-18 production in murine macrophages." (PMID 35345462, 2022). "In contrast, moM1 infection with virulent 22653/14 ASFV did not induce the release of either proinflammatory (IL-1α, IL-1β, IL-6, TNF-α) or anti-inflammatory (IL-10) or pro-Th1 (IL-12, IL-18) cytokines." (PMID 35215216, 2022). "Pro-inflammatory IL-1β, IL-6, and TNF-α cytokines increased in patients bearing hip prosthetics after infection with coagulase-negative staphylococci." (PMID 35203495, 2022). "None of the cytokines (IL-1β, TNF and IFNγ) were able to prevent the reduction in TEER upon infection with B. pertussis (data not shown)." (PMID 35256671, 2022). "Fluorescence imaging revealed that neither IL-1β, IL-6, nor LIF significantly modulated the percentage of eGFP+ hiNeurons or hiAstrocytes at 48 h post-infection." (PMID 36680128, 2022). "The concentration of certain cytokines, including CCL11, IL-1β, IL-5 and CXCL2 were similar between infected and control mice throughout the course of infection (not shown)." (PMID 35812400, 2022). "Median values of hBD-2 (V = 90, P < 0.001), RNase 7 (V = 286, P > 0.05), IL-1β (V = 749, P > 0.05) and IL-8 (CXCL-8) (V = 413, P < 0.001) increased during infection, but not for IL-6." (PMID 36382385, 2022).